INS (insulin)
Diseases named in the same sentence as INS in open-access papers (continued):
Sharing a sentence is not in itself a finding about the gene and the disease.
metabolic syndrome (continued). "Other recent studies have shown that Alzheimer’s disease (AD) is also more likely to be affected by insulin resistance in the nervous system due to a metabolic syndrome condition." (PMID 33477324, 2021). "Insulin action in cells is disrupted to varying extents, which can cause a wide spectrum of signs and symptoms such as increased weight/adiposity, high blood pressure, high blood glucose, excessive circulating insulin, chronic inflammation, and dyslipidemia." (PMID 34684300, 2021). "Nrf2 has been shown to improve glucose tolerance, insulin sensitivity and metabolic syndrome in rats and to inhibit oxidative stress and inflammatory reactions in the pancreas." (PMID 34371651, 2021). "Impaired mitochondrial function is commonly observed in DM and metabolic syndromes owing to β-cell mitochondria, which are fuel integrators of β-cells that generate signals for insulin secretion and regulate β-cell function." (PMID 33572166, 2021). "The metabolic syndrome impairs ketogenesis with higher mean insulin levels such that lower mean ketosis values are expected for many PD patients, perhaps by 20%; this is a consideration if a threshold effect exists for ketone body signaling." (PMID 34235637, 2021). "Other macrominerals, such as phosphorus, potassium, and magnesium, are involved in different components of the metabolic syndrome (e.g., insulin secretion)." (PMID 34836405, 2021). "Clinically, approximately 90% of diabetes patients have been diagnosed with T2DM, which is characterized by a reduction in insulin sensitivity and dysfunction of β-cells with hyperglycemia and dyslipidemia." (PMID 34248898, 2021). "The following variables had values of standardized difference >10%: age, nephropathy, eye diseases, dyslipidemia, insulin, meglitinide, acarbose, rosiglitazone, pioglitazone, statin and fibrate, suggesting potential risk of confounding from these variables." (PMID 34680039, 2021). "According to pathophysiological mechanisms, insulin is known as the headstream of metabolic syndrome." (PMID 34442386, 2021). "Insulin treatment significantly improved the dyslipidemia by lowering plasma levels of VLDL-TG, total cholesterol and LDL-C (p < 0.01 or less) and increasing plasma HDL-C (p < 0.0001) compared to NASH-STZ." (PMID 33596938, 2021). "Studies in mice have shown that SFCA supplementation improves insulin sensitivity and dyslipidemia, prevents weight gain, and increases energy expenditure in diet-induced obese mice." (PMID 34603565, 2021). "In this respect, more research is certainly needed with dihydroberberine to determine how well the greater plasma berberine levels improve dyslipidemia and glucose and insulin homeostasis as commonly reported in the literature." (PMID 35010998, 2021). "At the same time, the IL-22 pathway appears to have metabolic benefits, too, improving insulin sensitivity and decreasing endotoxemia, preventing the development of metabolic syndrome." (PMID 34886561, 2021). "In general, the normalizing effect on glucose metabolism is noted, consisting of an increase in insulin sensitivity and alleviation of metabolic syndrome." (PMID 34685538, 2021). "Nutrient excess and sedentary behaviors of our modern society are indications of metabolic syndrome, which significantly increases T2DM risk and gives a natural state of decreased insulin sensitivity and offers a common physiological β-cell challenge." (PMID 33490287, 2021). "MiRs levels correlated with serum insulin and HbA1c levels in individuals with T2D or MetS, and with higher BMI, dyslipidemia, and family history." (PMID 34199293, 2021). "In another study, feeding freeze-dried blueberry powder (1462 mg polyphenols for six weeks) also revealed improvements in insulin sensitivity in adults with metabolic syndrome." (PMID 33922576, 2021). "Supplementation with B. adolescentis in a rodent model of the metabolic syndrome has been shown to increase insulin sensitivity." (PMID 34365978, 2021).
metabolic syndrome (continued). "Previous clinical studies have also shown that fenofibrate affects the level of leptin in patients with dyslipidemia and hypertriglyceridemia and improves insulin sensitivity." (PMID 34988225, 2021). "In patients with metabolic syndrome, caloric restriction reduces body weight and exerts beneficial effects on insulin levels, fasting glucose levels, lipoprotein composition and pro-inflammatory cytokines within 6 months of intervention." (PMID 34660673, 2021). "In vivo studies demonstrated the involvement of the Rho GEFs P-Rex2, Vav2, Vav3 and PDZ-RhoGEF in glucose tolerance and/or insulin sensitivity, with deletion of these GEFs either contributing to the development of metabolic syndrome or protecting from it." (PMID 33923452, 2021). "Metabolic syndrome as a clustering disorder includes excess abdominal fat distribution, abnormal insulin and glucose metabolism, disturbed blood lipids, pro-inflammatory state, and hypertension." (PMID 33643564, 2021). "TWEAK knock-out mice enhanced insulin signaling in muscle and liver and protected them from ectopic fat deposits and dyslipidemia." (PMID 34764367, 2021). "To illustrate, following fecal microbiota transplantation from lean human donors to obese recipients with metabolic syndrome, a significant improvement in insulin sensitivity resulted." (PMID 33815293, 2021). "The specific contribution of hepatic steatosis to whole body insulin sensitivity and dyslipidemia is particularly significant for individuals diagnosed with the metabolic syndrome." (PMID 34861817, 2021). "The importance of sport in the management of metabolic syndrome was also emphasized by Schmidt-Trucksäss in 2006, and in 2016 Bird studied the insulin sensitivity at the muscle level observed lower in those who performed regular physical activity." (PMID 34829940, 2021). "Many studies illustrated that Blautia can drive insulin release and promote metabolic syndromes, such as hypertriglyceridemia, fatty liver disease, and IR." (PMID 34257691, 2021). "Age, waist circumference, follicle-stimulating hormone, insulin and sex hormone-binding globulin were predictive for dyslipidemia among Chinese women with PCOS." (PMID 34977197, 2021). "PPZ significantly inhibited the perturbed deviations in blood glucose concentration, HbA1c, C-peptide, plasma insulin, and ameliorated the lipid profile (dyslipidemia)." (PMID 34249262, 2021). "These mice exhibited reduced skeletal muscle mass and decreased responsiveness to insulin, leading to a metabolic syndrome-like condition." (PMID 33923452, 2021). "Insulin treatment attenuated dyslipidemia in NASH-STZ-HI hamsters and liver pathology was considerably improved compared to the NASH-STZ group, with prevention/reversal of hepatic steatosis, hepatic inflammation and stellate cell activation." (PMID 33596938, 2021). "Maternal obesity increases insulin and leptin resistance, dyslipidemia, hepatic inflammation, and steatosis in subsequent generation." (PMID 34828259, 2021). "Our results confirmed that age, WC, and insulin were predictors for dyslipidemia in Chinese women with PCOS." (PMID 34977197, 2021). "Thiamine decreased body weight and improved glycemia, insulin function, dyslipidemia, and activity of glyoxalase-I in MS rats with anti-glycation, antioxidant, and anti-inflammatory activities." (PMID 33995940, 2021). "It has been reported that in patients with diagnosed metabolic syndrome, the abnormalities in the circulating levels of irisin and its gene expression are related to BMI and markers of insulin sensitivity." (PMID 34680053, 2021). "Women in the mid-trimester dyslipidemia group had higher 30-min plasma glucose, higher 2hPG, and higher 2-h plasma insulin of the postpartum OGTT, higher postpartum TG, and higher postpartum LDL-c than those in the normal lipid group." (PMID 34429117, 2021).
metabolic syndrome (continued). "A clinical trial studying the effect of faecal transplant from lean donors to men diagnosed with the metabolic syndrome found that insulin sensitivity had improved and gut bacterial diversity had increased 6 weeks post transplantation." (PMID 34110438, 2021). "We also performed subgroup analyses based on the stratification by age, the presence of hypertension, dyslipidemia, use of insulin, and major comorbidities." (PMID 33619302, 2021). "Metabolic syndrome as a clustering disorder comprises of excess abdominal fat distribution, abnormal insulin and glucose metabolism, disturbed blood lipids, pro-inflammatory state, and hypertension." (PMID 33643564, 2021). "Fecal transplants from lean healthy donors were transferred to overweight patients with metabolic syndrome, which after six weeks showed improved hepatic and peripheral insulin sensitivity." (PMID 34007770, 2021). "Minor alleles of several TRPM5 SNPs, which are in linkage disequilibrium with rs886277, have been related to higher glucose level and reduced insulin sensitivity during an oral glucose tolerance test and metabolic syndrome." (PMID 33525598, 2021). "Metabolic syndrome as a set of central obesity, dyslipidemia, decreased insulin sensitivity and arterial hypertension has been established in 1988 and has been intensively studied ever since." (PMID 34557498, 2021). "One of the first indicators for causality regarding gut microbiome and metabolic syndrome was when the transfer of intestinal microbiota of lean donors to patients with metabolic syndrome increased the insulin sensitivity." (PMID 34072995, 2021). "NSE was also correlated positively with TC in the honey treated group, and with GPx in honey+insulin treated group showing the possible link between improvement in nerve function and reduction in dyslipidemia and oxidative stress." (PMID 33449943, 2021). "Elevated serum blood glucose, insulin levels, and dyslipidemia were significantly improved in diabetic rats by quercetin, resveratrol, and combination therapies." (PMID 33920079, 2021). "A high-fat diet can change the upper small intestinal microbiome, and the transplantation of a healthy gut microbiome to the upper small intestine of individuals with metabolic syndrome increases insulin sensitivity." (PMID 34684432, 2021). "The prevalence of insulin therapy during pregnancy in the mid-trimester dyslipidemia group was higher than that in normal lipid group (2.56 % vs. 1.31 %, P = 0.009)." (PMID 34429117, 2021). "It has been shown that high palmitate levels are present in the CSF of obese patients and patients with metabolic syndrome, and palmitate is able to induce a neuroinflammatory response with hypothalamic insulin and leptin resistance." (PMID 33946318, 2021). "As a producer of acetate, Blautia can drive the release of insulin and promote metabolic syndromes, such as hypertriglyceridemia, fatty liver, and IR." (PMID 34257691, 2021). "One study also showed that HOMA2-IR calculated with C-peptide was a more sensitive indicator for metabolic syndrome than HOMA2-IR calculated with insulin." (PMID 34579016, 2021). "In conclusion, using a pig model of metabolic syndrome, we show that a diet supplemented with beef fat enriched with VA has a mild insulin sensitizing effect while raising plasma HDL cholesterol." (PMID 34946118, 2021). "For the girls, elements of metabolic syndrome (uric acid and triglycerides) and parameters of insulin amount were more pronounced." (PMID 34205725, 2021). "Malnutrition and a sedentary lifestyle are the other reasons for dyslipidemia, but a prolonged increase in insulin levels ultimately leads to atherogenic dyslipidemia in different ways." (PMID 35223819, 2021). "Metabolic health was evaluated using the components of metabolic syndrome, along with insulin sensitivity/resistance, abdominal fat distribution, and intrahepatic fat content." (PMID 34869522, 2021).
metabolic syndrome (continued). "In recent years, there has been a lot of evidence to suggest that that increased serum FGF21 levels are found in obese, insulin-resistant patients, and those with metabolic syndrome." (PMID 34573919, 2021). "As metabolic syndrome progresses and the insulin insensitivity of peripheral tissues worsens, glycemic control is maintained for some time owing to a compensatory increase in beta cell insulin secretion." (PMID 35052168, 2021). "While the precise relationship between Se and dyslipidemia remains to be fully known, Se likely plays a role in dyslipidemia with an impact on insulin sensitivity, inflammation reaction, and oxidative stress." (PMID 34206577, 2021). "The authors report transient remission of metabolic syndrome, reducing body weight, BMI, waist circumference, and fasting glucose, as well as increasing insulin sensitivity in 50% of patients that received oral UA." (PMID 34439409, 2021). "In the present study, because of insufficient insulin data, evaluating the relationship between blood mercury levels and metabolic syndrome development was challenging." (PMID 34943283, 2021). "Previously, we reported evidence showing that chronic cola consumption in rats impairs pancreatic metabolism of insulin and glucagon and produces some alterations typically observed in the metabolic syndrome, with an increase in oxidative stress." (PMID 34115756, 2021). "It has been suggested that abdominal adipose tissue is the major source of plasma PAI-1, as it originates from adipose tissue in response to chronically elevated levels of TNF-α and insulin in individuals with metabolic syndrome." (PMID 34069933, 2021). "After just 2-weeks of a low-carbohydrate diet in an inpatient setting, ten obese individuals with T2D demonstrated dramatic reductions in blood glucose and insulin levels, along with improved insulin sensitivity, and dyslipidemia." (PMID 34684300, 2021). "These PCLSs were prepared from male C57BL/6J mice and cultured in varying concentrations of fructose, insulin, palmitic acid and oleic acid, to mimic metabolic syndrome." (PMID 34959755, 2021). "Induces metabolic syndrome-like phenotypes (impaired glucose and insulin functioning, hepatic steatosis, weight gain, increase in fat), oxidative stress and mitochondrial dysfunction." (PMID 34899613, 2021). "In another study, daily cellulose supplementation after a single-dose oral FMT in individuals with metabolic syndrome improved insulin sensitivity 6 weeks after treatment compared to baseline." (PMID 34737725, 2021). "The present study displays a comprehensive decrease in systemic inflammation coupled with a parallel decrease in fasting glucose, dyslipidemia, and insulin levels, after LGS." (PMID 33981153, 2021). "For girls, elements of metabolic syndrome (uric acid and triglycerides) and parameters of insulin amount were more pronounced." (PMID 34205725, 2021). "Reducing the risk of cardiometabolic complications has been stem from increasing insulin sensitivity, improving dyslipidemia and lowering blood pressure succeeding consumption of flaxseed and hesperidin." (PMID 33402222, 2021). "Traits associated with mitochondrial (MT) content include CHD, type 2 diabetes, and metabolic syndrome traits such as insulin sensitivity/resistance, obesity, and blood triglycerides." (PMID 34099068, 2021). "The increase of LPS and release of proinflammatory cytokines results in metabolic endotoxemia, which promotes the development of metabolic syndrome, including impaired insulin signaling and chronic low-grade inflammation." (PMID 34975748, 2021). "A study evaluating serum insulin levels over eight years in children and young adults showed that dyslipidemias were three times more common in patients with hyperinsulinemia." (PMID 33494341, 2021). "The administration of UA resulted in the remission of metabolic syndrome by lowering body weight, waist circumference, fasting glucose, and insulin sensitivity." (PMID 34885816, 2021).
metabolic syndrome (continued). "FXR agonist administration in the rabbit metabolic syndrome model can reduce the insulin resistance of adipose tissue." (PMID 35250844, 2021). "Nevertheless, we observed that individuals with contrasting MetF to an OGTT had similar metabolic health, assessed by the clinical markers of metabolic syndrome, insulin sensitivity/resistance indexes, and intrahepatic fat content." (PMID 34869522, 2021). "All the main markers of the metabolic syndrome inherent in these mice were normalized: reduced body weight, decreased fasting glucose and insulin concentrations, and improved glucose tolerance." (PMID 34959419, 2021). "Women with PCOS are often insulin resistant leading to impaired glucose tolerance (IGT), metabolic syndrome, and dyslipidemia which markedly increases the risk of developing diabetes and cardiovascular disease (CVD)." (PMID 33997590, 2021). "Elevated Body Mass Index (BMI), insulin, blood glucose, dyslipidemia and hypertension were noted in OPPs chronic exposed groups." (PMID 33652791, 2021). "Fasting blood glucose is considered as the main indicator of the dyslipidemia, while the body mass index, glycated hemoglobin, fasting insulin, triglycerides, and cholesterol are regarded as the secondary indicators." (PMID 33663065, 2021). "Among the diabetic subjects, themean time since the DM diagnosis was 73.4 ± 74.0 months; 4 (13.3%) subjectshad renal failure, 21 (70.0%) had dyslipidemia, and 5 (16.7%) used insulin." (PMID 33567012, 2021). "As a possible therapeutic approach, maintaining muscle mass by exercise training is well established to improve glycemic control, insulin sensitivity, and metabolic syndrome." (PMID 33220490, 2021). "The abundance of Roseburia increase in the feces of obese individuals with metabolic syndrome who receive fecal transplants from lean metabolically healthy donors, and this strategy improved peripheral insulin sensitivity." (PMID 33815293, 2021). "Our results were as expected, since the typical dyslipidemia of insulin resistant state involves hypertriglyceridemia and low HDL." (PMID 33021758, 2021). "A randomized, double-blind, placebo-controlled clinical trial was performed on 24 patients between 30 and 60 to investigate the effects of UA (150 mg) on metabolic syndrome, insulin sensitivity and inflammation." (PMID 34885816, 2021). "4‐HIL has the effects of promoting insulin secretion, improving the resistance of peripheral tissues to insulin, and regulating dyslipidemia, which is mainly used in the pharmaceutical industry." (PMID 32625042, 2020). "Like adiponectin, adipolin can impact the metabolic syndrome by attenuating atherosclerosis and improving insulin sensitivity, as reviewed elsewhere." (PMID 32375340, 2020). "There is great interest towards the modulation of the gut microbiota in metabolic syndrome, as two studies reported promising results in improving peripheral insulin sensitivity." (PMID 32517023, 2020). "Further, BAT FAU in cold was directly associated with whole-body insulin sensitivity, indicated by M-value, and HDL-cholesterol levels indicating that subjects with high BAT fatty acid metabolism possess lower risk of the metabolic syndrome." (PMID 32873825, 2020). "The authors assessed a decrease of insulin sensitivity in recipients who received FMT from donors with metabolic syndrome compared with using post-surgical donors." (PMID 32517023, 2020). "Hyperandrogenism is correlated to a high tolerance to insulin 32-34, which can lead to insulin level increases and other metabolic syndromes." (PMID 32913460, 2020). "After further adjustments for metabolic syndrome components, fasting insulin, and hs-CRP were made, the differences in the IMT-mean of the cystatin C levels became borderline significant and remained significant across albuminuria categories." (PMID 33129312, 2020).